CRP (C-reactive protein)
Diseases named in the same sentence as CRP in open-access papers (continued):
Sharing a sentence is not in itself a finding about the gene and the disease.
infection (continued). "In fact, a high CRP level without any obvious infection was observed in 25.6% of the AC events." (PMID 32782279, 2020). "C-reactive protein (CRP) is the first APR to be discovered, whose plasma concentrations at baseline are less than 2–3 μg/ml, but can rapidly increase up to 1000-fold upon infection or tissue injury; the heightened levels of CRP, however, return to the baseline with the resolution of inflammation." (PMID 32223889, 2020). "This could be explained by the imperfect sensitivity of CRP but could also be due to GAS carriage rather than active infection." (PMID 31889507, 2020). "In terms of laboratory tests at early infection stages, three patients had a decreased WBC, one third of the patients had an increased neutrophil ratio and decreased lymphocyte ratio, and most patients had elevated CRP levels, generally consistent with previous reports." (PMID 33361525, 2020). "Finally, peak procalcitonin and peak CRP concentrations beyond 48 hours did not always precede actual occurrence of severe complications and infections." (PMID 32127631, 2020). "The study concluded that CRP often does not normalise even when the infection is eradicated." (PMID 32089975, 2020). "The optimal CRP cut-off level in the current study was relatively low, suggesting that CRP level increases may not occur solely as a result of infection." (PMID 32782279, 2020). "Accordingly, it was hypothesized that in individuals in whom the conformation of CRP remains unchanged, perhaps due to inappropriate inflammatory conditions around CRP, CRP is not fully functional during infection." (PMID 33552084, 2020). "Importantly, ESR and CRP are nonspecifically elevated by infection, and they remain normal in more than a third of RA patients at presentation irrespective of disease activity." (PMID 32461558, 2020). "Unlike CRP, IL-6 can also help to distinguish infection from fever of unknown origin in pediatric practice." (PMID 31795299, 2019). "In addition, the decrease in CRP levels in cases in which no organisms were identified by joint aspiration was seen in 60% of group L patients and 100% of group D patients; infection control rates were 100% for both groups." (PMID 31651331, 2019). "As CRP is more reflective of any acute inflammation or even an infection than resolution of inflammation, we could not find any changes in CRP with FO supplementation in this study." (PMID 30684965, 2019). "A high negative predictive value in this regards is extremely important since CRP level may be elevated also in absence of infection." (PMID 30800122, 2019). "Similarly, the combination of CRP and PV together gave no improvement in AUC, compared with the better of the two individual tests, for infection or cancer." (PMID 31208975, 2019). "The CRP mutant protected mice against infection regardless of the time of administration into mice." (PMID 30863393, 2019). "Mouse models of H. influenzae infection have not been established yet to determine whether CRP protects against infection with H. influenzae." (PMID 30863393, 2019). "The lack of CRP elevation in our study could reflect low frequency of diarrhea in our children and indicates that they had probably passed the acute phase of infection." (PMID 31442248, 2019). "The group with low total cholesterol and high CRP had a poorer prognosis relative to that of the group with high cholesterol and low CRP; the former may reflect a poor prognosis due to severe infection-triggered AE-IPF rather than untriggered AE-IPF." (PMID 31086028, 2019). "Additionally, serum ESR, CRP, and IL-6 had no benefit in predicting persisting infection before second-stage prostheses implantation." (PMID 31159792, 2019). "However, as far as we know, biomarkers used for diagnosis of PJI, e.g., serum erythrocyte sedimentation rate (ESR), C-reactive protein (CRP), synovial fluid analysis, and intraoperative frozen section, have limited values in predicting persistent infection at reimplantation." (PMID 31711522, 2019).
infection (continued). "CRP is a non-specific acute phase marker in inflammation, infection and tissue damage." (PMID 30797230, 2019). "Moreover, the IG percentage adds to WBC and CRP in the early exclusion of infection and can be obtained routinely without extra blood sampling or costs." (PMID 30344287, 2018). "Values for CRP and s-alb was altered to such an extent during the last month of life that they, in the absence of clinical signs of infection, may be used as a complementary indication of short remaining life time." (PMID 29534089, 2018). "We compared the characteristics and serial suPAR and CRP concentrations of patients with and without an infection using Chi-squared, Fisher’s exact, t-test and Mann-Whitney tests as appropriate, and calculated the area under the receiver operating characteristics curve (AUC)." (PMID 30071826, 2018). "Thus, the aim of this study was to evaluate whether the measurement of IG percentage is a useful predictive marker of serious bacterial infections (SBI) when compared with conventional infection markers such as WBC, CRP, and ANC in pediatric patients." (PMID 30344287, 2018). "Therefore, this information could be helpful in diagnosing postoperative infection in the earlier time period with combination of basic screening tests such as ESR and CRP." (PMID 29439725, 2018). "As a clear limitation to this study, other features, that might indicate infection persistence such as pus and the CRP, were not considered." (PMID 30009171, 2018). "In another study indicating that serum CRP levels were more effective than the other inflammatory markers, 123 IDFUs were evaluated and the roles of serum PCT and CRP levels in IDFU were evaluated and only serum CRP levels were found to be effective in grading the severity of the infection." (PMID 29675434, 2018). "Moreover, the performance of IG measurement compared with conventional infection markers, such as white blood cell count (WBC), absolute neutrophil count (ANC), and C-reactive protein (CRP) remains unclear." (PMID 30344287, 2018). "Moreover, the level of preoperative CRP can be elevated from fracture itself or elevated in various clinical situations, such as concomitant cardiac disease, without an obvious infection." (PMID 29854731, 2018). "Inflammatory proteins in the blood, including C-reactive protein (CRP), haptoglobin, serum amyloid A, fibrinogen, and alpha 1-acid glycoprotein, help restore homeostasis and reduce microbial growth independently of antibodies during trauma, stress, or infection." (PMID 29467962, 2018). "As clinical signs andsymptoms of infection and laboratory parameters are often inconclusive and someserum biomarkers are elevated in non-infective inflammatory processes, procalcitonin(PCT) and C-reactive protein (CRP) have been studied as novel biomarkers ininfectious and inflammatory diseases." (PMID 29846409, 2018). "However, since clinicians often employ CRP, WBC, and ANC as part of routine care to decide the etiology of infection, it was reasoned that the comparator method may be impaired if the panelists were blinded to these data." (PMID 29700762, 2018). "The ESR and serum CRP level are not specific measures of infection." (PMID 27402464, 2017). "Serum protein CRP was not correlated with the aorta diameter, because its levels could be affected by multiple factors related to nonspecific inflammation or infection and not only by aortic tissue damage." (PMID 29158612, 2017). "When combining the positive results of any two tests, we found the probability of infection was 100% (except CRP + IL-6 and IL-6 + ESR) but with low probability of occurrence (the rate among infected nonunion patients was CRP + ESR: 25.7%; CRP + WBC: 17.1%; IL-6 + WBC: 20%; WBC + CRP: 11.4%)." (PMID 29130050, 2017). "CRP has long been recognized as an acute-phase reactant; in contrast, kallistatin has been observed to be a negative acute-phase protein in patients with severe infection." (PMID 28542440, 2017).
infection (continued). "Inflammatory syndrome was less pronounced (erythrocyte sedimentation rate [ESR]: 62 vs. 81 mm at 1 h; p = 0.03; C-reactive protein [CRP]: 60 vs. 147 mg/L; p = 0.0003) and less common (ESR < 30 mm: 23% vs. 0%; p = 0.01; CRP < 10 mg/L: 23% vs. 0%; p = 0.005) compared to patients with SA infections." (PMID 29029624, 2017). "First, while this study focused on the association between a single measurement of maternal CRP concentrations at the time of admission and infection-related and inflammatory intra-amniotic complications, it did not take into consideration the trend of CRP concentrations during latency." (PMID 28813455, 2017). "We have also not discussed in detail other markers of infection such as CRP." (PMID 28114931, 2017). "In terms of the individual biomarkers, CRP is a sensitive but nonspecific biomarker of systemic inflammation in response to a variety of pro-inflammatory conditions, including infection, trauma, surgery, burns, tissue infarction, advanced cancer, and chronic inflammatory conditions." (PMID 28355230, 2017). "Regrettably, however, the number of patients studied was limited (n=8), and the delay to reoperation in cases with uncontrolled infection was not reported, limiting the conclusions that can be drawn regarding the usefulness of CRP values in this particular population." (PMID 28226029, 2017). "Furthermore, mean CRP was higher in those with single-strain (33.2 mmol/L) compared to mixed-strain infection (10.3 mmol/L) at start-of-treatment, albeit not significantly (P = 0.08, Welch’s t-test)." (PMID 29096618, 2017). "CRP, a non-specific acute reactant protein of inflammation, is synthesized in hepatocytes and in response to release of cytokines, such as interleukin 6 release by monocytes and other immune cells under infection, tissue necrosis, and inflammatory disease." (PMID 27104127, 2016). "A CRP < 5 mg/L rules out serious infection and could be used by GPs to avoid unnecessary hospital referrals." (PMID 27716201, 2016). "We therefore interrogated the diagnostic and prognostic value of both CRP and TNF-α in enhancing the clinical distinction between 1) critically ill patients with and without a clinically defined SIRS, and 2) with and without infection." (PMID 28469676, 2016). "Second, we could not exclude subjects with active infection or inflammation, or those with elevated inflammatory markers such as white blood cell counts or C-reactive protein." (PMID 27070153, 2016). "Finally, more attention should be paid to reimplantation of spacers in patients without clinical symptoms of infection with prolonged elevated level of CRP and in cases of prior infectious process of operated joint." (PMID 27015812, 2016). "In spite of strict control on exclusion criteria, nevertheless, the presence of localized inflammation or infection in a number of patients with elevated serum CRP could not be ignored." (PMID 26958331, 2016). "Point-of-care (POC) C reactive protein (CRP) testing for patients with suspected LRTI has been included in guidelines in Norway, Sweden, the Netherlands, Germany, Switzerland, Czech Republic and Estonia to determine severity of infection and extent of inflammation." (PMID 26940107, 2016). "Unlike IgG, FcγRIIA affinity for CRP is actually reduced in individuals homozygous for FcγRIIA-131H and this may influence outcomes in infection." (PMID 27909648, 2016). "However, these 3 pigs did not have any other signs of infection and had normal CRP levels in the following measurements." (PMID 27830761, 2016). "We also often encounter ADPKD patients with slight elevation of CRP although they do not have obvious cyst infection, and such slight CRP elevation might be due to minor intracystic bleeding or inflammation rather than infection." (PMID 27829402, 2016).
infection (continued). "In terms of individual-level risk factors, children with parasitaemia (with or without high CRP) were more likely to be under 2 years of age, be stunted or wasted, and/or have higher ferritin concentration at baseline compared to children without infection." (PMID 27391972, 2016). "However, of the 80 children referred to hospital to rule out serious infection, 24 (30.7 %, 95 % CI, 19.6–45.6 %) had a CRP < 5 mg/L." (PMID 27716201, 2016). "We also aimed to investigate how CRP results should be interpreted; specifically, whether a low CRP level can rule out infection and the consequent need for hospital referral." (PMID 27716201, 2016). "CRP and elevated WBC may both be induced by cerebral ischaemia associated with acute stroke in the absence of infection." (PMID 26937636, 2016). "We hypothesized that in the critically ill patient with suspected infection the diagnostic accuracy of the simply obtainable ICIS is at least equivalent in this respect to WBC, CRP and PCT, without requiring extra blood sampling." (PMID 27384242, 2016). "Our findings suggest that activation markers, particularly CRP, may have a role in identifying good response to TB therapy regardless of the strain of infection and could be further developed as point-of-care tests." (PMID 26951717, 2016). "Moreover, omentin concentrations did not correlate with markers of inflammation or infection such as C-reactive protein (CRP), procalcitonin (PCT), and interleukin-6 (IL-6)." (PMID 27867249, 2016). "Hence, CRP and SAA levels may serve as good indicators for the magnitude of infection with E. canis during the acute phase of the disease." (PMID 25888870, 2015). "However, the ‘pathology’ in this case is CVD and not frank infection (during which CRP levels are closer to 10–100 mg/l)." (PMID 26675298, 2015). "Lastly, a group with elevated CRP but without infection was not enrolled as controls." (PMID 26259626, 2015). "CRP monitoring in the early period after surgery might have a limitation in detecting late onset SSI, which might have a hematogenous origin or result from the intraoperative seeding of microbes, with infections remaining subclinical for an extended period." (PMID 25888882, 2015). "Thus, when SLE patients exhibit elevations of both serum CRP level and C4d/CR1 ratio on admission, the cooccurrence of infection and disease flare-up may be suspected." (PMID 26273660, 2015). "Therefore, taken together, using the CRP level as a guide for empirical choice of antibiotics or to rule out serious infections or withhold antibiotic therapy is not recommended." (PMID 26259626, 2015). "Following I.V. injection, CRP levels were significantly higher in mice injected with FNN compared to controls and non-pregnant females which may have been due to an increased inflammatory response to infection by FNN." (PMID 25806806, 2015). "A normal CRP response to therapy, or absence of secondary rise after surgery, may help to exclude infection." (PMID 26502877, 2015). "The cause of persisting infection was a nonsensitive spacer in a patient with methicillin-resistant S. aureus (MRSA) in one case, persistent fistula in two cases, and persistently high C-reactive protein levels in one case." (PMID 25428415, 2014). "However, it should be emphasized that serum CRP is a nonspecific marker of inflammation and infection." (PMID 24877114, 2014). "The higher levels of CRP with lower concentrations of leukocytes in CVA16-infected patients indicated that leukocyte activation, rather than leukocyte redistribution, may occur in patients with CVA16 infection." (PMID 24776922, 2014). "Inflammatory markers as ESR and CRP may also suggest the diagnosis of infection, but no clear relationship to the ratios has been noted." (PMID 24548622, 2014). "CRP was also measured to ensure SF was not affected by infection." (PMID 25006582, 2014). "Traditional infection markers, CRP, were neither related to SOFA nor to APACHE II score." (PMID 24883317, 2014).
infection (continued). "Additionally, in cases of multiple lung nodules for which infection or metastasis cannot be confirmed, the serum levels of SCC-Ag and CRP could help clinicians choose the appropriate management." (PMID 25061977, 2014). "Moreover, C-reactive protein test was not used to screen school children for the presence of infection or inflammation." (PMID 25438147, 2014). "Estradiol treatment of castrated rats seems to enhance bactericidal defence mechanisms most, as reisolation of P. multocida showed the lowest colony numbers, and decreased CRP and WBC count could mean that the infection was less severe due to estradiol pre-treatment." (PMID 25001579, 2014). "Evidence-based antibiotic prescribing can be promoted in several ways, one of which could be the application of point-of-care testing (POCT) for C-reactive protein (CRP), an acute-phase protein that shows increased levels in serum during infection and tissue damage." (PMID 24886066, 2014). "Since CRP does not cross the placental barrier, it may therefore be useful in diagnosing infections in newborns." (PMID 24659848, 2014). "Differentiating between aseptic implant loosening and implant failure due to an infection can be difficult, because the standard laboratory parameters for infection (serum CRP concentration or leukocyte count) can be negative in infectious cases and thus misleading." (PMID 24795505, 2014). "Besides persistent swelling and local hyperthermia, there were no systemic signs of an infection (normal leukocyte count and normal serum level of C-reactive protein (CRP))." (PMID 24641471, 2014). "Thus, if an infection is clinically suspected, as in the current case, it is required to rule out inflammation using markers like CRP." (PMID 25514884, 2014). "Furthermore, if there is an absence of systemic signs of infection (i.e., fever, elevated white cell count, or CRP), then infection is unlikely." (PMID 24719845, 2014). "Unlike CRP and IL-6, IL-8 showed a significant increase only in the infected neonates when compared to the non-infected and control neonates indicating that it is increased only in infection and not in inflammation." (PMID 23869218, 2013). "Our analyses of patient characteristics between those with and without postoperative infections showed that age, ASA, total operation time, blood loss, surgical procedure, CRP levels (POD1), preoperative ADN levels, and ADN ratio were significantly different between groups." (PMID 23520452, 2013). "Regarding infection, no fever was observed, while CRP and ESR were in normal range." (PMID 23984124, 2013). "However, on admission, 33% of the noninfected patients had CRP concentrations greater than 7.9 mg/dL, making it difficult to discriminate patients with and without infection based on this CRP measurement." (PMID 24286072, 2013). "Like CRP, both the infected and non-infected neonates showed a significant increase of IL-6 when compared to the control neonates at all time intervals indicating that it is increased both in infection and inflammation." (PMID 23869218, 2013). "The presence of infection in patients with SCA could also increase CRP levels (this was not addressed in this study)." (PMID 24223742, 2013). "One of the most important aspects of the study is indirect evidence that PCT may have potential utility as a useful marker for the detection of infection in patients with increased CRP resulting from active non-specific urticarial inflammation." (PMID 23207551, 2013). "However, serum CRP levels were not discriminative between surviving infected mice and non-surviving infected mice, and therefore CRP is not a biomarker for fatal outcome of infection." (PMID 23520553, 2013). "Other fetal markers of infection as umbilical cord CRP have not been evaluated." (PMID 23894452, 2013).